ABCC4 (ATP binding cassette subfamily C member 4 (PEL blood group))
Description:
ATP-dependent transporter of the ATP-binding cassette (ABC) family that actively extrudes physiological compounds and xenobiotics from cells. Transports a range of endogenous molecules that have a key role in cellular communication and signaling, including cyclic nucleotides such as cyclic AMP (cAMP) and cyclic GMP (cGMP), bile acids, steroid conjugates, urate, and prostaglandins. Mediates the ATP-dependent efflux of glutathione conjugates such as leukotriene C4 (LTC4) and leukotriene B4 (LTB4) too. The presence of GSH is necessary for the ATP-dependent transport of LTB4, whereas GSH is not required for the transport of LTC4. Mediates the cotransport of bile acids with reduced glutathione (GSH). Transports a wide range of drugs and their metabolites, including anticancer, antiviral and antibiotic molecules. Confers resistance to anticancer agents such as methotrexate.
Synonyms: MOAT-B; MOATB; MRP4; EST170205
Tractability: Small molecule: a structure with a bound ligand is known; it belongs to a druggable protein family. Antibody: UniProt places it where antibodies can reach, with high confidence; its Gene Ontology location is reachable by antibodies, with high confidence; UniProt predicts a signal peptide or a membrane-spanning region; the Human Protein Atlas places it where antibodies can reach. PROTAC: ubiquitination databases record sites on it; its protein half-life has been measured; a small molecule that binds it is known.
Target class: ABCC subfamily; ATP-binding cassette; Transporter; Primary active transporter
Chemical probes: BI-4926 (high quality)
Safety:
Unwanted effects reported when the protein is acted on. In parentheses: how it was acted on, where the effect was seen, and who reports it.
ADR (source: ClinPGx)
adverse drug reactions (source: ClinPGx)
adverse drug reactions, in particular neutropenia/ leukopenia and gastrointestinal toxicity (source: ClinPGx)
drug toxicity (source: ClinPGx)
gastrointestinal toxicity (source: ClinPGx)
Kidney disease (source: ClinPGx)
leukopenia (source: ClinPGx)
mucositis (source: ClinPGx)
nephrotoxicity (source: ClinPGx)
neutropenia (source: ClinPGx)
neutropenia/ leukopenia (source: ClinPGx)
Osteonecrosis (source: ClinPGx)
plasma level (source: ClinPGx)
require glucarpidase treatment (source: ClinPGx)
toxicity and plasma level (source: ClinPGx)
Gene: Protein-coding gene on chromosome 13 (95,019,835 to 95,301,822, reverse strand). Ensembl gene ENSG00000125257.
Subcellular location: Basolateral cell membrane; Apical cell membrane
Subcellular location (Human Protein Atlas): Plasma membrane; Golgi apparatus; Vesicles
Pathways (Reactome):
Drug ADME: Azathioprine ADME; Paracetamol ADME
Hemostasis: Platelet degranulation
Transport of small molecules: ABC-family protein mediated transport
Gene Ontology:
Molecular function: ABC-type 3',5'-cyclic GMP transmembrane transporter activity; ABC-type bile acid transporter activity; ABC-type glutathione S-conjugate transporter activity; ABC-type xenobiotic transporter activity; ATPase-coupled transmembrane transporter activity; efflux transmembrane transporter activity; glutathione transmembrane transporter activity; guanine nucleotide transmembrane transporter activity; prostaglandin transmembrane transporter activity; protein binding; purine nucleotide transmembrane transporter activity; urate transmembrane transporter activity; xenobiotic transmembrane transporter activity; 15-hydroxyprostaglandin dehydrogenase (NAD+) activity; ABC-type transporter activity; ATP binding; ATP hydrolysis activity; transmembrane transporter activity
Biological process: bile acid and bile salt transport; cAMP transport; cilium assembly; export across plasma membrane; leukotriene transport; prostaglandin secretion; prostaglandin transport; urate transport; platelet degranulation; transmembrane transport; transport across blood-brain barrier; xenobiotic metabolic process; xenobiotic transmembrane transport; glutathione transmembrane transport; guanine nucleotide transmembrane transport
Cellular component: apical plasma membrane; basolateral plasma membrane; membrane; plasma membrane; platelet dense granule membrane; external side of apical plasma membrane
Genetic constraint (gnomAD): Loss-of-function variants: 77 observed, 143.87 expected, observed/expected ratio (o/e) 0.54, 90% interval 0.44 to 0.65. The upper end of that interval is the gene's LOEUF score, 0.65, which puts it in group 2 of 6, group 1 being the genes least tolerant of losing a copy. Missense variants: 1,238 observed, 1,477.3 expected, observed/expected ratio (o/e) 0.84, 90% interval 0.8 to 0.88. Synonymous variants: 545 observed, 550.74 expected, observed/expected ratio (o/e) 0.99, 90% interval 0.92 to 1.06.
Gene-disease validity (ClinGen):
ClinGen rates the evidence that ABCC4 causes each of these diseases.
qualitative platelet defect (autosomal recessive): Moderate.
Homologues: Orthologues: chimpanzee ABCC4 (99% identical), macaque ABCC4 (97% identical), rabbit ABCC4 (90% identical), dog ABCC4 (89% identical), guinea pig ABCC4 (89% identical), mouse Abcc4 (87% identical), rat Abcc4 (87% identical), zebrafish abcc4 (69% identical), tropical clawed frog abcc4 (67% identical), Drosophila melanogaster Mrp5 (45% identical), Drosophila melanogaster CG7627 (44% identical), Drosophila melanogaster Mrp4 (43% identical), and 8 more. Paralogues in human: ABCC1 (37% identical), ABCC2 (36% identical), ABCC3 (35% identical), ABCC5 (34% identical), CFTR (34% identical), ABCC10 (32% identical), ABCC12 (32% identical), ABCC6 (32% identical), ABCC11 (32% identical), ABCC8 (32% identical), ABCC9 (31% identical).
Diseases named in the same sentence as ABCC4 in open-access papers:
ABCC4 is named in the same sentence as 143 diseases in open-access papers, as found by Europe PMC text mining. Sharing a sentence is not in itself a finding about the gene and the disease. The quoted sentences say what the papers report.
cholestasis (28 papers, 2012 to 2025). Impairment of the bile flow caused by obstruction within the liver, or outside the liver in the bile duct system. "ABCC4 expression increases with hepatic cholestasis and accumulation of liver toxins, suggesting on involvement in the efflux of toxic substances to protect the liver from damage." (PMID 40658709, 2025). "It is also known that low physiological MRP4 (ABCC4) expression levels markedly increase during cholestasis as a part of an adaptative response that consists in the basolateral efflux of BAs to compensate BSEP and MRP2 dysfunctions." (PMID 40064699, 2025). "The mouse model used in this study with CCl4 administered for 1 year underwent severe cholestasis with increased Abcc3 and Abcc4 levels, which corresponds to the findings of previous studies." (PMID 38053838, 2023).
breast carcinoma (24 papers, 2013 to 2025). "Variants of ABCC4 (rs9561778) showed a significant association with cyclophosphamide-induced adverse drug reactions in breast cancer patients." (PMID 30363999, 2018). "In summary, our results show that ABCC1 plays a role in breast cancer proliferation, whilst ABCC4 has a greater role in cellular migration and invasion." (PMID 33081264, 2020). "Our results suggest that ABCC1 is important for breast cancer proliferation, whilst ABCC4 has a greater role in cellular migration and invasion." (PMID 33081264, 2020). "The ABCC4 gene was also identified to play a role in cellular migration of breast cancer cell line models MCF-7 and MDA-MB-231." (PMID 33334016, 2020). "Using both small molecule inhibitors and siRNA knockdown of ABCC1 and ABCC4, we investigated the impact of these transporters on the proliferation, clonogenic capacity, migration, and invasion of the breast cancer cell lines." (PMID 33081264, 2020). "Taken together, these data suggest that CUL4A is a critical component in chemoresistance, and H19, CUL4A, ABCB1 and ABCC4 work coordinately to display the action on modulation of multidrug resistance in breast cancer cells." (PMID 29190892, 2017). "In this study, the role of ABCC1 and ABCC4 in breast cancer progression was investigated." (PMID 33081264, 2020). "In this study, the aim was to investigate whether ABCC1 or ABCC4 play a role in the proliferation or migration of breast cancer cell lines MCF-7 (luminal-type, receptor-positive) and MDA-MB-231 (basal-type, triple-negative)." (PMID 33081264, 2020). "The export of PGE2 has also been suggested as a potential mechanism by which ABCC4 might be important in breast cancer." (PMID 33081264, 2020). "ABCC1 and ABCC4 have previously been implicated as negative prognostic indicators for breast cancer." (PMID 33081264, 2020). "Finally, we investigated the efflux of S1P, as levels of S1P have previously been implicated in breast cancer, and both ABCC1 and ABCC4 are capable of transporting S1P." (PMID 33081264, 2020). "However, less is known about whether ABCC1 and ABCC4 have a role in breast cancer development and/or progression." (PMID 33081264, 2020). "Therefore, preliminary investigations into how ABCC1 and/or ABCC4 might elicit their effects on breast cancer cell proliferation and migration were undertaken." (PMID 33081264, 2020). "Therefore, in this study, we investigated whether ABCC1 or ABCC4 are involved in cellular proliferation or migration in breast cancer cell lines." (PMID 33081264, 2020). "In contrast, breast cancer exhibited relatively lower deep deletion rates, restricted to ABCG2, ABCC4, ABCA2, ABCC2, and ABCC9." (PMID 40641097, 2025). "Deep deletions were significantly more prevalent in prostate cancer tissues compared to breast cancer tissues, where they were relatively rare and limited to ABCG2, ABCC4, ABCA2, ABCC2, and ABCC9." (PMID 40641097, 2025). "Deep deletions were significantly more prevalent in prostate cancer than in breast cancer, with frequent occurrences in ABCG2, ABCG1, ABCC4, ABCA2, ABCC2, ABCC7/CFTR, and ABCC9." (PMID 40641097, 2025). "Data obtained from the TCGA database also showed a statistically significant lowered average expression level of the ABCB1, ABCC4, ABCC6, and ABCG2 genes in patients with breast cancer compared to the control group." (PMID 36674773, 2023). "Similar to its effects on ABCC4 mRNA, miR-381-3p targets the 3′UTR of ABCB1 mRNA and promotes cisplatin sensitivity in breast cancer cells This suggests that miR-381-3p is involved in the posttranscriptional regulation of other xenobiotic transporters." (PMID 35753353, 2022). "For metformin, the highest number of its targets were associated with malignant neoplasm of the prostate (six genes) and breast carcinoma (seven genes: ABCB11; ABCC2; ABCC3; ABCC4; DHFR; DPP4; SLC22A1)." (PMID 36046822, 2022).
breast carcinoma (continued). "MK571, which inhibits both ABCC1 and ABCC4, and Reversan, which inhibits ABCC1, were the only inhibitors to affect the proliferation of the breast cancer cells." (PMID 33081264, 2020). "Further in cancers that display increased expression of ABCC4 and MPP1 (e.g., breast cancer and medulloblastoma), our findings suggest that disrupting the interaction between MPP1 and ABCC4 can improve the cytotoxicity of conventional therapy against tumors." (PMID 29146910, 2017). "Thus, in assessing the metastatic potential of miR-124 in breast cancer, the ABCC4 (ATP-binding cassette subfamily C member 4) target gene was identified." (PMID 36362406, 2022). "However, the same report suggests that the knockdown of ABCC4 in MBA-MB-231 cells does decrease the PGE2 efflux and that this is important for breast cancer metastasis." (PMID 33081264, 2020). "Non-resistant breast cancer cells augmented the expression of ABCC10, but not ABCC4, after their incubation with a single dose of cisplatin." (PMID 35205642, 2022).
prostate carcinoma (21 papers, 2008 to 2025). A carcinoma that arises from epithelial cells of the prostate gland. "Among these proteins, ABCC4/MRP4 has been identified as a key player; however, the association between its expression and immune response in prostate cancer remains elusive." (PMID 39247809, 2024). "The pioneer TF FOXA1 and GATA2 have been previously linked to the regulation of ABCC4 expression in prostate cancer, where MRP4 has been validated as a clinically relevant prognostic marker associated with metastasis." (PMID 39114357, 2024). "PCAT92 shares the locus on chromosome 13 with ABCC4 gene, known to be implicated in prostate cancer." (PMID 30197753, 2018). "Interestingly, ABCC4 was also upregulated in the prostate cancer samples, suggesting the role of ABCC4 as a primary causative factor of docetaxel resistance." (PMID 40282556, 2025). "A recent prostate cancer study discovered that the inhibition of ABCC4 of the ABC transporter family improved the sensitivity of docetaxel against resistant cancer cells." (PMID 40282556, 2025). "Immunohistochemical information from the HPA database showed that higher staining of GSTM4, PLP1, and PTGS2 was found in normal prostate tissue, while higher staining of SLC27A2, SLC45A3, APOE, and ABCC4 was observed in prostate cancer tissue." (PMID 40861808, 2025). "Next, we analyzed patients' survival and found that low expression of ABCC4 indicated better overall survial for prostate cancer patients both in TCGA database and in our own Tongji Cohort." (PMID 39247809, 2024). "We also confirmed the ABCC4 expression difference in tumors and adjacent normal tissues of prostate cancer." (PMID 39247809, 2024). "In this study, we introduce the multi-drug resistance protein ABCC4/MRP4 as a key player prominently expressed in prostate cancer, exerting a pivotal role in suppressing the activity of intratumoral CD8+ T cells." (PMID 39247809, 2024). "Depletion of ABCC4 in prostate cancer cells halts the release of prostaglandin E2 (PGE2), a molecule that diminishes the population of CD8+ T cells and curtails their cytotoxic capabilities." (PMID 39247809, 2024). "Expression of MRP4 protein followed the same pattern as ABCC4 mRNA in prostate cancer cells and renal cell carcinoma." (PMID 39412582, 2024). "We first examined ABCC4 expression across all kinds of cancer in TCGA database and found that it was only in prostate cancer extremely high expressed compared to that in adjacent normal tissues." (PMID 39247809, 2024). "As shown by research in prostate cancer, inhibition of ABCC4 expression restores the docetaxel sensitivity." (PMID 34094932, 2021). "PCAT92 and ABCC4 falls under this category as they both were found to be co-expressed in multiple prostate cancer samples." (PMID 30197753, 2018). "Expression of ABCC4 is significantly higher in prostate cancer cells as compared to adjacent benign cells suggesting that the gene is either merely linked with cancer or that the gene is somehow involved with the formation and progression of cancer." (PMID 30197753, 2018). "It has been determined that the expression of ABCC4 is positively correlated with androgen levels in prostate cancer patients." (PMID 30197753, 2018). "Our work here have showcased that PCAT92 is upstream in the pathway which leads to the overexpression of ABCC4 in prostate cancer." (PMID 30197753, 2018). "It has been shown that PCAT92 and ABCC4 are up-regulated in prostate cancer samples from multiple transcriptome datasets." (PMID 30197753, 2018). "Enrichment of PI3K-Akt pathway suggests one possible mechanism by which PCAT92 and ABCC4 are playing role in prostate cancer." (PMID 30197753, 2018). "PCAT92 knockdown in LNCaP cells inhibits both cell viability, cell proliferation and ABCC4 protein expression suggesting a role for PCAT92 in prostate cancer via the regulation of ABCC4." (PMID 30197753, 2018).
prostate carcinoma (continued). "Addition of androgens in prostate cancer cells significantly upregulated ABCC4 and the addition of anti-androgens decreased expression." (PMID 30197753, 2018). "In this respect, recent studies have shown that MRP4/ABCC4 is overexpressed in several solid tumors such as prostate cancer, non-small cell lung cancer, aggressive primary neuroblastoma, and pancreatic cancer." (PMID 25301721, 2014). "This suggests that ABCC4 ablation inhibits prostate cancer in an inmmune response-dependent manner." (PMID 39247809, 2024). "Moreover, high expression of ABCC4 in prostate cancer cells was assosiated with low CD8+ T cell infiltration." (PMID 39247809, 2024). "Moreover, due to its high expression specificity, ABCC4 has great potential to become a target for prognosis prediction and intervention therapy of prostate cancer." (PMID 39247809, 2024). "Multidrug resistance-associated protein 4 (ABCC4), an ATP-binding cassette transporter, and arachidonate 15-lipoxygenase B (ALOX15B), an enzyme involved in lipid metabolism and inflammation, have been known to decrease in prostate cancer and with tumor progression." (PMID 40559998, 2025). "Conversely, the marked overexpression of the transporter protein ABCC4 in prostate cancer, compared to other solid tumors, indicates that the preferential export of pge2 from cancer cells is the predominant source of its elevated levels in prostate cancer (over-export)." (PMID 39247809, 2024). "Together, these observations and localization in the nucleus suggests that PCAT92 may play a role in prostate cancer by increasing the local concentration of ZIC2 by forming RNA-DNA triplex near ABCC4 promoter thus helping in recruitment of ZIC2 for ABCC4 regulation." (PMID 30197753, 2018). "In contrast, prostate cancer tissues exhibited frequent deep deletions in ABCG2, ABCG1, ABCC4, ABCA2, ABCC2, ABCC7/CFTR, and ABCC9." (PMID 40641097, 2025). "We also examined the ABCC4 expression in multiple human prostate cancer cell lines and identified DU145 with highest ABCC4 expression." (PMID 39247809, 2024). "To investigate the specific function of ABCC4, we depleted it in both DU145 cells (human prostate cancer) and RM1 cells (murine prostate cancer)." (PMID 39247809, 2024). "Substrates of ABCC4 include DHEA-S, and the expression of ABCC4 in primary prostate cancer tissue was reported to be reduced upon androgen ablation, suggesting a role for AR in regulating expression of ABCC4." (PMID 32584883, 2020). "Out of these not only was ZIC2 among the top three transcription factor based on significance but is also significantly overexpressed in prostate cancer tissues and cell lines like PCAT92 and ABCC4." (PMID 30197753, 2018). "It was reported that PCAT92, ABCC4 and ZIC2 are overexpressed in multiple prostate cancer datasets in the public repository (SRP002628 and ERP000550)." (PMID 30197753, 2018). "The similar effect on cell viability and cell proliferation under both ABCC4 and PCAT92 knockdown condition suggests that both genes are involved in same pathway in prostate cancer." (PMID 30197753, 2018). "In LnCAP prostate cancer cells, FOXA1 and GATA2 independently bind to the ABCC4 gene and recruit chromatin loop-forming factors such as MED1 from distal sites to the cluster two region, allowing androgen receptors to bind and promote transcription upon hormone stimulation." (PMID 39114357, 2024). "Another prostate cancer cell line, PC3 showed the least expression of ABCC4, PCAT92 and ZIC2." (PMID 30197753, 2018). "However, genetic ablation of ABCC4 did not promote apoptosis nor inhibit growth of prostate cancer cells in vitro." (PMID 39247809, 2024).